MTOR (mechanistic target of rapamycin kinase)
Diseases named in the same sentence as MTOR in open-access papers (continued):
Sharing a sentence is not in itself a finding about the gene and the disease.
cancer (continued). "AKT1 and 2 are linchpin signal transducers in the PI3K/AKT/MTOR pathway, and represent central players in proliferative and anti-apoptotic signaling in many cancers, including breast cancer." (PMID 39030258, 2024). "Studies have shown that Drp1 expression is upregulated in a variety of cancers and that Drp1 is associated with several metabolic pathways leading to cancer, including the PI3K-Akt, MAPK/ERK1/2, mTOR, AMPK, and Wnt/β-cyclin pathways." (PMID 39507763, 2024). "Examples of such targetable aging pathways in cancer include the mammalian target of rapamycin (mTOR), Sirtuins, AMPK (AMP-activated protein kinase), and PRC2." (PMID 38879847, 2024). "We also found that the anti-cancer effect of ICA was associated with the promotion of autophagy, possibly via ICA activation of the AMPK/mTOR/ULK1 pathway." (PMID 38355608, 2024). "This pathway regulates cancer cell survival and growth, and mTOR is a direct substrate of AKT kinase." (PMID 38360682, 2024). "Particularly implicated in crucial biological processes like cancer survival, migration, and invasion, FAK also regulates proliferative activities involving PI3K, Akt, mTOR, Ras, and ERK/MAPK in various cancers." (PMID 38791186, 2024). "According to recent data, dormant cancer cells are also characterized by suppressed mTOR kinase activity." (PMID 38418814, 2024). "PI3K/AKT/mTOR pathway activity was extensively reported as a driver of therapy resistance in multiple cancers and different treatment contexts." (PMID 38473300, 2024). "TMES3 was particularly sensitive to immunotherapy, with upregulated fatty acid metabolism, cancer-related pathways, cytokine pathways, and mTOR pathways." (PMID 38565865, 2024). "And, deregulated mTOR signaling in cancer has been revealed to affect tumor immune microenvironment." (PMID 39290706, 2024). "On the other hand, considering the dual roles of autophagy in cancer, some autophagy activators are also suggested in cancer therapy, such as the mTOR inhibitor rapamycin and the AMPK activator palbociclib." (PMID 38891049, 2024). "Oleuropein exhibits a more variable profile; it can either decrease levels of tumor suppressors like SIRT1 or alter oncogene expressions such as KRAS and mTOR, depending on the cancer type." (PMID 39203892, 2024). "To summarize, it can be observed that mTOR signaling plays an important role as a molecular regulatory factor in connecting metabolic disorders and cancer in chronic HBV infection." (PMID 39247820, 2024). "c-Myc, Cyclin E, c-Jun, Notch1, and mTOR are among the oncogenic proteins that specifically facilitate ubiquitination and proteasomal destruction, making them moniker cancer suppressors." (PMID 39528487, 2024). "Celastrol promotes the suppression of the tumors and triggers autophagy in cells with cancer via modulating signaling networks including Akt/mTOR, Beclin‐1, NF‐κB, ROS, HSP90, MAPK, and the proteasome." (PMID 39436197, 2024). "Glutamine acts as another signaling molecule for mTOR activation, which leads to cancer cell proliferation, suppression of apoptosis, and mediated autophagy, which is observed in TNBC." (PMID 39852119, 2024). "There are multiple studies showing that inhibiting the mTOR/AKT pathway is promising against cancer and M. tb via the regulation of autophagy." (PMID 39457551, 2024). "Despite mTOR hyperactivity in many cancers, some cytoplasmic regulators prevent mTOR activity, thereby preventing tumor growth." (PMID 38892329, 2024). "mTOR-dependent mitochondrial translocation of TFEB suggests that the efficacy of mTOR inhibitors used in the clinic as immunosuppressant and in cancer therapy is possibly dependent on the mitochondrial activity of TFEB." (PMID 38263327, 2024).
cancer (continued). "Previous studies have highlighted the significant role of the MTOR gene in tumorigenesis and cancer progression." (PMID 39742278, 2024). "In general, patients with cancer after LT are usually subjected to either immunosuppressive drug minimization or a switch to or combination with mTOR inhibitors, which has been proven to have better outcomes in certain types of neoplasia." (PMID 39272917, 2024). "The PI3K/AKT/mTOR signaling pathway also crosstalks with estrogen and androgen receptors, amplifying their transcriptional activity and promoting cancer cell proliferation." (PMID 39770406, 2024). "Baicalin restrains cancer cell proliferation by targeting apoptotic pathway and tumor growth related pathway such as phosphoinositide 3-kinase/protein kinase B/mammalian target of rapamycin (PI3K/Akt/mTOR) and Wnt/β-catenin signaling." (PMID 39354529, 2024). "Apart from cancer, mTOR inhibitors have also shown promising results in the treatment of genetic disorders such as tuberous sclerosis complex (TSC) and potential benefits in the treatment of neurodegenerative diseases such as Alzheimer’s disease." (PMID 38892329, 2024). "The dual sword role of metformin, on one hand, known to activate AMPK – which in turn inhibits mTOR and suppresses proliferation—but, on the other hand, has also the potential to increase cancer progression, illustrates the intricacy of this relationship." (PMID 38835644, 2024). "The key route for metformin’s anti-cancer effects involves the stimulation of the AMPK/mammalian target of rapamycin (mTOR) pathway, which is initiated by the suppression of complex I within the mitochondrial respiratory chain." (PMID 39000122, 2024). "These alterations modulate upstream/downstream intracellular cell growth signaling such as MAPK and mammalian target of rapamycin (mTOR), modify the cell cycle checkpoints, inhibit apoptosis, and alter DNA replication, thereby enhancing cancer cell growth." (PMID 39850800, 2024). "The LKB1-AMPK pathway has been shown to promote cancer cell survival in response to acute nutrient stress by inhibiting mTOR, leading to the induction of autophagy." (PMID 39538085, 2024). "The preclinical findings in murine endothelial cells provide a basis for further research into tetrandrine's potential as a targeted therapy for diseases involving dysregulated PI3K/AKT/mTOR signaling, including certain cancers." (PMID 38327657, 2024). "The intricate dynamics between mTOR and glycolysis in cancer encompass both direct and indirect mechanisms." (PMID 39394200, 2024). "After cancer diagnosis, a significant prognostic impact was derived from the shift to mTOR inhibitors compared to a definitive IS drug suspension (p = 0.004)." (PMID 39228659, 2024). "Approximately 30% of cancers utilize the mTOR signaling pathway, contributing significantly to their development and advancement by influencing cell cycle regulation, growth, survival, and metabolism." (PMID 39056712, 2024). "In this review, we will explore the importance of mTOR signaling in metabolic diseases and cancers, as well as the most recent findings on mTOR inhibitors and their clinical implications." (PMID 38892329, 2024). "mTOR, as a crucial nexus governing cellular growth, metabolism, and proliferation, is an established drug target, particularly in cancer." (PMID 38727317, 2024). "The mTOR pathway plays a pivotal role in regulating cellular translation, and its dysregulation is frequently observed in cancer, including AML." (PMID 38690164, 2024). "Twelve different cancer drug compounds in 6 different categories, including mTOR inhibitors, DNA inhibitors, MT inhibitors, HSP90 inhibitors, HDAC inhibitors, and proteasome inhibitors, were used for combination screening." (PMID 38475728, 2024). "Previous studies confirmed that UBE2C plays an important role in various malignancies and affects cancers through the PI3K/Akt/mTOR signaling pathways." (PMID 38690615, 2024).
cancer (continued). "(b) ATO and APA inhibit cancer progression via modulation of VEGFR2/Akt/mTOR and Akt/GSK-3β/c-Myc signaling pathway." (PMID 39223679, 2024). "Previous study confirmed that UCK2 is essential for maintaining the stability of mTOR and downregulation of UCK2 can specifically inhibit mTOR signaling pathway-related metabolic reprogramming of cancer cells." (PMID 39179560, 2024). "Further research and clinical trials are needed to validate the efficacy and safety of using miRNAs targeted at mTOR as therapeutic agents in combination with RT, ultimately translating these findings into improved clinical outcomes for cancer patients." (PMID 38965615, 2024). "The results offer new possibilities for treating cancer by targeting malignancies using pDNA/tachyplesin and activating the mTOR and NFκB signaling pathways." (PMID 38691208, 2024). "In recent years, small molecule inhibitors targeting AKT and mTOR have been developed for cancer treatment." (PMID 38319449, 2024). "Under the action of PI3K, AKT, and mTOR inhibitors, the proliferation of cancer cells was blocked, and apoptosis was increased." (PMID 38167649, 2024). "In summary, the intricate modulation of the mTOR pathway by ridaforolimus presents diverse implications in cancer treatment, pain management, and antiviral strategies, emphasizing its multifaceted role in cellular processes." (PMID 38584599, 2024). "Heightened mRNA expression levels of mEAK-7 have been observed in several cancer cell lines and there is significant elevation of both mEAK-7 and mTOR signaling in tumor and metastatic lymph nodes of patients diagnosed with NSCLC." (PMID 38532930, 2024). "Rapamycin, also known as sirolimus, is considered a first-generation allosteric mTOR inhibitor and has been approved for the treatment of several types of cancers." (PMID 38892329, 2024). "The findings of this study align with previous research on the beneficial role of mTOR or AKT inhibition in cancer." (PMID 38952771, 2024). "PI3K-Akt-mTOR is often dysregulated in cancer, leading to enhanced survival and proliferation of tumor cells." (PMID 39483536, 2024). "Following bufalin treatment, cancer cells reorganize the translation of specific mRNAs involved, notably, in the mTOR pathway that contributes to the emergence of a population of cells insensitive to MAPKi, also known as persistent cells." (PMID 38178183, 2024). "Activation of the EGFR/MAPK/mTOR/AKT/ERK1/2 signaling pathway has been reported to promote cancer cell growth, survival, and metabolism." (PMID 38762741, 2024). "The potential of Beclin-1 as a viable target for cancer therapy is highlighted by its associations with key autophagy regulators such as AMPK, mTOR, and ATGs." (PMID 39650649, 2024). "Since the current study shows that treatment with Z. nummularia ethanolic extract upregulates AKT/ mTOR activity, it suggests an adaptive response to treatment to allow repair and promote cancer cell survival." (PMID 38531974, 2024). "It is shown that the PI3K/Akt/mTOR pathway is triggered in TNBC, and PI3K/Akt/mTOR pathway inhibitors can inhibit the tumor growth of TNBC and cause the apoptosis of cancer cells conversely." (PMID 38526702, 2024). "SLC7A5 expression supports cancer progression, mostly by supplying essential amino acids to cancer cells, resulting in the activation of the mammalian target of rapamycin (mTOR) pathway to promote tumor proliferation." (PMID 38281999, 2024). "miRNA-mediated regulation of the mTOR signaling pathway is also related to enhancing chemosensitivity efficacy in cancer patients." (PMID 38965615, 2024). "The activation of AMPK and the PI3K/AKT/mTOR pathway induces autophagy and apoptosis in cancer cells, including the NCI-H295R cell line." (PMID 38539429, 2024). "PI3K/AKT/mTOR signaling pathway dysregulation is found in various pathologies, including cancer progression such as in GC." (PMID 38339127, 2024).
cancer (continued). "For example, autophagy can be promoted by suppressing the autophagy-related mTOR pathway, thus supporting cancer cells growth." (PMID 38575922, 2024). "AMPK agonists like metformin and AICAR activate this pathway, disrupting mTOR signaling and reducing cancer cell migration and proliferation." (PMID 39682234, 2024). "Proliferation-related mammalian target of rapamycin (mTOR) signaling was activated, and Ki67 frequency was three-fold augmented in positive correlation with metastasis and cancer stage, respectively." (PMID 39337548, 2024). "The phosphatidylinositol 3-kinase/protein kinase B/mammalian target of the rapamycin (PI3K/Akt/mTOR) signaling pathway axis is one such pathway that plays a major role in the regulation of cell growth critical in both normal and cancer cells." (PMID 38542151, 2024). "Since these sole treatments utilizing mTOR pathway inhibitors only have been faced with limitations especially in efficacy, there have been combinational approaches for enhanced anti-cancer therapy." (PMID 39349424, 2024). "This review provides an overview of the current understanding of miRNAs targeting mTOR as therapeutic agents to enhance RT outcomes in cancer patients." (PMID 38965615, 2024). "Drugs like BEZ235, an mTOR/PI3K dual inhibitor, are being investigated to enhance chemotherapy responses by reversing EMT and decreasing markers associated with cancer stem cells." (PMID 39770406, 2024). "Although PI3K/AKT/mTOR signaling has been established as a key regulator of proliferation, cancer, longevity, and mitochondrial homeostasis, its role in mediating platelet hyperreactivity in MPNs has not been previously reported." (PMID 38060311, 2024). "This further emphasizes the vast role mTOR signaling plays in cancer metabolism and the importance of gut microbial composition in improving gut functions and preventing carcinogenic pathways." (PMID 38892329, 2024). "Our SNU449 xenograft and PDX HCC models demonstrate that SMYD5 depletion alone significantly suppresses cancer growth, and renders them hypersensitive to mTOR suppression." (PMID 39103523, 2024). "Everolimus has antiproliferative effects in cancer cell lines and animal models and inhibits mTOR well." (PMID 38421832, 2024). "Meanwhile, MTOR was found to be linked to PIK3C; BRAF and MAPK1 were found to be linked to EGFR; and ERBB2 and ALK are linked to the common NSCLC and Cancer pathway." (PMID 38921583, 2024). "Its mechanisms of action, including AMPK activation and mTOR pathway inhibition, indicate a promising role in cancer prevention and treatment." (PMID 39272875, 2024). "Chemotherapy is well known to promote the emergence of dormant cancer cells, often referred to as drug-tolerant persisters which are characterized by both down- and upregulated mTOR signaling." (PMID 38418814, 2024). "The PI3K/Akt-mammalian target of rapamycin (mTOR) pathway is one of the intracellular pathways aberrantly upregulated in cancers including hematopoietic malignancies." (PMID 38743735, 2024). "Oncogenic signaling, including the PI3K/mTOR pathway and cancer-associated KRAS mutant, markedly elevates SG formation to enhance cancer cell fitness." (PMID 38731625, 2024). "mTOR signaling is one of the most commonly affected cascades in human cancers, and data in solid tumors showed that it is dysregulated in almost 30% of cancers." (PMID 38539200, 2024). "We further identify adaptive tactics cancer cells employ under low-oxygen conditions to maintain energy production and growth, particularly emphasising the crucial role of mTOR activation." (PMID 39207627, 2024). "In any case, the general trend of transcriptomic alterations induced by YWF is in line with our report that YWF create a false satiety signal via mTOR, preventing cancer cells from recruiting essential coping mechanisms." (PMID 39266717, 2024).
cancer (continued). "Overall, the strategic inhibition of c-MET and pathways like mTOR show promise in treating various cancers by overcoming resistance and enhancing therapeutic outcomes." (PMID 39329778, 2024). "The phosphoinositol three kinases/protein kinase B/mammalian target of rapamycin (PI3K/AKT/mTOR) pathway is widely known to be altered in a great majority of cancers, including OC." (PMID 38727322, 2024). "The PI3K/AKT/mTOR signaling pathway is critical in regulating cell survival, proliferation, and growth in various cellular contexts, including cancer." (PMID 38213733, 2024). "In addition, pathway enrichment analysis of their results showed that exercise training in cancer survivors was able to induce a hypomethylated signature in pathways associated with DNA replication/repair, the cell cycle, transcription, translation, proteosome and mTOR signalling." (PMID 39272925, 2024). "Mutations and activation of protein members within the PI3K/Akt/mTOR pathway are commonly found in cancer." (PMID 39519596, 2024). "The PI3K/AKT/mTOR signaling pathway is a very important signaling pathway in cancer biology and plays a central role in cell growth, proliferation, metabolism, and survival." (PMID 38259082, 2024). "Noteworthy transformations have been observed due to the overexpression of mTOR’s target, eIF4E, in rodent fibroblasts, consequently prompting extensive investigations into mTOR’s role in cancer." (PMID 37760640, 2023). "In cancer, including gliomas, the PI3K/Akt/mTOR signaling pathway is dysregulated due to the loss of the tumor suppressor PTEN or constitutively active PI3K and Akt mutants." (PMID 36973040, 2023). "Taken together, our results showed that circATP9A can directly bind with HuR to increase the expression level of NUCKS1, further activating PI3K/AKT/mTOR signaling and promote cancer progression." (PMID 38049814, 2023). "Due to the metabolic reprogramming, the interaction between PI3K/AKT/mTOR and the metabolism can also alter the immune suppression network, which is widely present in different cancers." (PMID 36768977, 2023). "The next group of drugs described herein is mTOR inhibitors, already used in immunosuppression and cancer treatment." (PMID 37958470, 2023). "Based on the new mechanisms described and their apparent conservation in several types of cancer, we explored combined NUAK1 and Akt or mTOR inhibition to avoid compensatory mechanisms that result in cancer cell survival and resistance to chemotherapy." (PMID 38135881, 2023). "As a downstream molecule of the PI3K/AKT pathway, mTOR signaling is commonly activated in tumors and controls cancer cell metabolism by altering expression and/or activity of a number of key metabolic enzymes." (PMID 37007127, 2023). "The therapeutic effects of NPs on mTOR can be used to modify it, and this knowledge can be used to develop safe and efficient NPs-based cancer metabolism therapies." (PMID 36597205, 2023). "It has been amply proven in recent years in cancer patients and animal models that mTOR malfunction promotes carcinogenesis." (PMID 37513916, 2023). "mTOR is an important link in the cellular signaling process, and mTOR signaling plays a key role in human cancers." (PMID 37773165, 2023). "Abnormal activation of the PI3K/AKT/mTOR signaling pathway promotes the occurrence and progression of various cancers and plays a key role in the treatment of tumor drug resistance." (PMID 38115126, 2023). "Here, we discuss the developments for the therapeutic targeting of mTOR signaling with improved anticancer efficacy for the benefit of cancer patients in clinics." (PMID 37779156, 2023). "Apitolisib, a novel oral PI3K/mTOR inhibitor developed by Genentech, has shown anti-tumour activity in breast, prostate, endometrial, and other cancers by blocking the cell cycle and thereby inducing apoptosis." (PMID 37489050, 2023).